MMP9 (matrix metallopeptidase 9)
Diseases named in the same sentence as MMP9 in open-access papers (continued):
Sharing a sentence is not in itself a finding about the gene and the disease.
cancer (continued). "The overexpression of MMP-9 in the invasive front of different malignant tumors is linked to poor clinical outcome." (PMID 23183822, 2012). "In fact, increased MMP-9 levels have been reported to be closely associated with high stages of cancer in various human tissues, including UC-UUT." (PMID 22928942, 2012). "Among MMPs, MMP-2 and MMP-9 have mainly been associated with malignant tumor progression and metastasis in both human and canine tumors." (PMID 21726449, 2011). "The reported association of the KU80/MMP-9 complex with the invasiveness of cancer cells is the first evidence linking DNA repair proteins with cellular invasiveness." (PMID 21283680, 2011). "Genes associated with the metastatic ability of cancer stem cells, especially Muc-1, MMP9 and Myc, were strongly reduced by CD44 knockdown." (PMID 22152097, 2011). "Despite overexpression and invasion promoting ability of Lewis (y), and MMP-2 and MMP-9 being separately reported in various types of human cancer, a direct association between Lewis (y) and these two TIMPs has never been described." (PMID 21151448, 2010). "Previous studies have shown that one of the mechanisms underlying SDF-1-induced cancer cell invasion is activation of MMP-9 and MMP-2." (PMID 21167057, 2010). "The molecular-genetic studies of the functional −1562 C/T polymorphism of the MMP9 gene brought about interesting results in cardiovascular, cancer, and neuropsychiatric conditions." (PMID 20037727, 2009). "Increased OPN and VEGF levels, activation of p-c-Met and p-Akt, and enhanced expressions of NF-κB and MMP-9/MMP-2 are associated with cancer cell growth, invasion, and metastasis as well as angiogenesis." (PMID 19796390, 2009). "A subgroup of MMPs, the gelatinases (MMP-2 and MMP-9), have been particularly implicated in progression, angiogenesis and metastasis of various cancer types." (PMID 18506186, 2008). "Although degradation of basement membranes is not a function that is concordant with the usual clinical behaviour of LCIS (a non-invasive, low-risk cancer precursor), we suspect that the activity of MMP9 in LCIS must be tightly regulated." (PMID 18954444, 2008). "Additionally, rosemary extracts modulate the expression of cancer-associated genes, particularly by downregulating matrix metalloproteinase-9 (MMP-9) and tissue inhibitor of metalloproteinase-1 (TIMP-1), both implicated in cancer progression." (PMID 41150809, 2025). "The relevance of MMP9 mRNA expression in predicting TNBC and LUAD patient outcome, suggests that EV-associated MMP9 could possibly identify circulating EVs in cancer patients." (PMID 39910665, 2025). "Loss of TKs5 results in lower MMP9 levels and reduced invasive capacity in cancer cells." (PMID 40575485, 2025). "The research targets key cancer-associated proteins, Matrix Metalloproteinase-9 (MMP9) and Glucose-Regulated Protein 78 (GRP78), identified through expression analysis, functional network mapping, and pathway enrichment as critical mediators of cancer progression and metastasis." (PMID 40679956, 2025). "Elevated expression of MMP9 is linked to poor prognosis in cancer patients." (PMID 41472816, 2025). "In particular, we found that in the lung a trend toward an increase in VIM, as well as of the CDH5, MCAM, and MMP2 mRNAs associated with the metastasis-derived cancer cell lines, whereas the MMP9 gene seemed to be mainly related to the mesenchymal phenotype of these cells." (PMID 40332096, 2025). "MMP2 and MMP9 are closely associated with the metastasis of malignant tumor cells." (PMID 38430256, 2024). "MMP9 and MAPK14 might also be related due to MAPK14 and MMP-9 being associated with cancer development." (PMID 38974913, 2024). "The participation of the MMP9 axis was lately studied in association with miRNA and circRNA, where inhibition of MMP9 protein degradation by miRNA-516a promoted cancer metastasis, and MMP9 upregulation in circ0001361-overexpressed BC cells promoted cell migration and invasion." (PMID 38372785, 2024).
cancer (continued). "This prospective, randomized, single-center trial aimed to assess the impact of anesthesia techniques and drugs on serum expression of NETosis markers (H3Cit, MPO, and NE), as well as other markers implicated in cancer dissemination (MMP-9 and VEGF-A) at 3 h post-surgery." (PMID 38678209, 2024). "In various cancers, MMP9 and SCGN were associated with immune-related molecules and immune cells." (PMID 38375034, 2024). "MMP-9 is most associated with its role in degrading extracellular matrix components in cancer." (PMID 38922117, 2024). "Given the association between MMP-9 and cancer progression, the modulation of MMP-9 release by Ahsg may indirectly affect cancer invasion and metastasis." (PMID 39684629, 2024). "Further studies revealed that CypA promotes HCC cell adhesion and metastasis through up-regulating MMP-3 and MMP-9.54,104 Thus, the current studies suggest that the up-regulation of CypA and MMPs is associated with various types of cancer, and CypA appears to play a vital role in cancer metastasis." (PMID 39513594, 2024). "Among others, the expression of MMP-2 and MMP-9 proteins in CRC tissue as potential biomarker roles is underlined due to their correlation with important clinical data: cancer grade, higher risk of dissemination or disease recurrence, and shorter patient survival." (PMID 39337393, 2024). "MMP-9 has been implicated in the progression and metastasis of various cancers." (PMID 39062099, 2024). "MMP-2 and MMP-9, in particular, have been associated with cancer metastasis." (PMID 38884093, 2024). "Among these, MMP2 and MMP9 are the most significant cancer-associated zinc-dependent endopeptidases involved in the invasion and metastasis of various carcinomas and elevated expression levels of activated MMP2 or MMP9 have been correlated with metastasis in patients with PCa." (PMID 39336161, 2024). "In addition, matrix metalloproteinase 9 (MMP9) is associated with malignant tumour progression and invasion." (PMID 38057406, 2023). "The findings of the current study could provide the basis for further investigation on MMP-9 as a novel diagnostic tool and therapeutic target for inducing liver regeneration in patients with malignant hilar biliary obstruction." (PMID 36837539, 2023). "Moreover, SHN3 expression strongly correlated with IL13Rα2 and MMP9-associated poor prognosis in different cancers." (PMID 37963919, 2023). "In mammals, mmp9 is thought to be closely associated with cancer." (PMID 36833402, 2023). "In addition, probiotic supernatants inhibited the activity of matrix metalloproteinase 9 (MMP-9) linked to cancer risk." (PMID 37835359, 2023). "Androgen receptor (AR) knockout mice showed higher incidence of metastatic prostate tumors and higher corresponding levels of CCL2 while other studies have shown that AR knockout causes a significant increase in MMP9 which has been indicated for its role in cancer metastasis." (PMID 36836690, 2023). "MMP-2 and MMP-9 gene polymorphisms may affect their biological function, and thus their role in cancer development and progression." (PMID 37445754, 2023). "Furthermore, only TWEAK-treated GBM cells exhibited increased expression of integrins, as well as MMP9, all of which are associated cancer markers." (PMID 37567906, 2023). "MMP-2 and MMP-9 promoter polymorphisms can affect mRNA and protein expression levels by modifying transcriptional activity, eventually leading to the development of several types of cancer, including breast, lung, esophageal, and colorectal cancer." (PMID 37445754, 2023). "Higher MMP9 levels were associated with worse overall survival in cancer patients (left)." (PMID 35589683, 2022). "As an example, NET-associated neutrophil elastase and matrix metallopeptidase 9 (MMP9) could awaken dormant cancer cells, thereby promoting invasion and metastases." (PMID 35371088, 2022).
cancer (continued). "It is possible that intracellular MMP9 may be linked to cancer growth, at least in part, by its participation in TLR-4-dependent regulation of innate immunity and inflammation." (PMID 35406619, 2022). "We believe that such a technology may find future use in multiple diseases where MMP2/MMP9 gelatinases are overexpressed and play a pathogenic role (including cancer)." (PMID 35401813, 2022). "Furthermore, we found that C1632 suppressed the phosphorylation of focal adhesion kinase (FAK) and the expression of matrix metalloproteinase‐9 (MMP‐9), which have been widely implicated in the adhesion, invasion, and migration of cancer cells." (PMID 34913237, 2022). "The overexpression of MMP9 was confirmed as intimately associated with cancer metastasis." (PMID 36497431, 2022). "In addition to that, in these papers, the relations between MMP-2, MMP-7, and MMP-9 polymorphisms and the risk of a variety of cancers were evaluated." (PMID 35574300, 2022). "The overexpression and dysregulation of MMP-9 are associated with migration and invasion in cancer." (PMID 35723293, 2022). "Significant associations between variants in the MMP-2, MMP-7, and MMP-9 and cancer risk." (PMID 35574300, 2022). "In cancer cells, the protein overexpression of NF-κB has been associated with the promotion of invasion and migration by increasing its downstream NF-κB targets, such as MMP9, Hpa, and VEGF." (PMID 36364935, 2022). "Therefore, in order to obtain more accurate conclusions, this integrative meta-analysis for evaluating the relations of MMP-2, MMP-7, and MMP-9 variants with the risk of cancer was conducted." (PMID 35574300, 2022). "MMP-2 and MMP-9 are reported to be associated with cancer cell invasion and metastasis." (PMID 36333531, 2022). "Finally, 135 articles on MMP-2, MMP-7, and MMP-9 polymorphisms related to cancer risk were included in the meta-analysis, among which 36,530 were cases and 41,258 were controls." (PMID 35574300, 2022). "Several plasma-based EC biomarker candidates were also captured in this library and include adipokines (e.g., adiponectin), plasma lipoproteins (apolipoproteins, plasma amyloid A), matrix metalloproteinases (MMP-9) and cancer-associated antigens (MUC 1, MUC 16 etc)." (PMID 34359700, 2021). "Besides, MMP9 expression correlates with abnormal collagen deposition associated with chronic diseases, including various cancers and cardiovascular diseases." (PMID 33542744, 2021). "However, it is generally thought to have an oncogenic effect through being involved in the regulation of a wide range of genes associated with hallmarks of cancers, including upregulation of MMP9." (PMID 33572115, 2021). "Similarly, the overexpression of Fn14 contributes to multiple malignant cellular phenotypes associated with cancer progression in androgen-independent PCa cell lines, in part controlled by the tissue remodeling enzyme matrix metalloproteinase 9 (MMP-9)." (PMID 34572917, 2021). "The matrix metalloproteinase type 9 (MMP-9 or gelatinase B) has been implicated in the development and progression of some types of cancer such as prostate, bladder, colorectal, and lung, due to its ability to degrade type IV collagen and gelatin, which are the main components of the BM." (PMID 35097136, 2021). "Such an association between galectin-7 and MMP-9 has been observed in many cancer types." (PMID 34198494, 2021).
cancer (continued). "In addition, NET-associated proteases, NE and matrix metalloprotease 9 (MMP9), awaken dormant cancer cells and facilitate cancer cell metastasis." (PMID 34237033, 2021). "TNF-α expression was observed to upregulate expression of several cancer-associated genes in the epithelial cells which include extracellular matrix (ECM) remodeling genes such as MMP9, PLAU, FN1 and ICAM1, chemokines such as CCL2, CXCL2, CXCL3 and CXCL10 and regulatory genes such as UBD and PTGS2." (PMID 34946170, 2021). "Investigation focused on the functional mechanism underlying KLK7 suggested that it could cleave pro-MMP9-generating active MMP9 and induce the shedding of cell adhesion proteins so as to mediate cancer cell proliferation and invasion." (PMID 32076707, 2020). "In addition, AG and GG genotypes of MMP-9 rs17576 are both associated with increased cancer risk in postmenopausal women." (PMID 33146350, 2020). "MMP-9 overexpression is traditionally associated with cancer aggressiveness and poor prognosis." (PMID 32455575, 2020). "Beyond EMT, evaluation of AHR-regulated expression and activity patterns revealed several targets implicated in cancer progression, including members of the matrix metalloprotease family (MMPs, MMP9 and MMP24), asparagine synthetase (ASNS) and the ATF4 transcription factor." (PMID 33214553, 2020). "In addition, acting as downstream targets of MAPKs, MMP2 and MMP9 were also highly induced when circ_0032821 was upregulated in GC cells, thus causing the cancer cell invasion." (PMID 32165864, 2020). "MMP-2 (gelatinase A) and MMP-9 (gelatinase B) are both cancer associated." (PMID 32765634, 2020). "In addition, the ruthenium-phloretin complex was able to control cell proliferation and boosted apoptotic outbursts in cancer cells associated with the increase in cellular response towards Bax while diminishing responses towards Bcl-2, NF-κB, and MMP-9." (PMID 32566099, 2020). "Cancer-associated neutrophils appear to play a role in malignant angiogenesis and invasion, which are processes associated with the ability of these cells to secrete several proteases involved in extracellular matrix remodeling, i.e., MMP-9." (PMID 33171792, 2020). "Also, in cancer survivors, MMP9 and Osteopontin (both associated with pro-tumoral processes) levels were associated with a lack of access to care." (PMID 32587352, 2020). "The potential inhibition of migration and invasion by B. nigra extract was also evidenced by the downregulation of MMP2, MMP9 and Snail genes, and upregulation of E-cadherin gene (hallmark of cancer metastasis) in a concentration-dependent manner at the transcriptional and translational levels." (PMID 32365503, 2020). "Thus, the microgravity environment up-regulated expression of MMP-2 and MMP-9, which cause cancer cell migration." (PMID 31601869, 2019). "Furthermore, the previously study also noted that MMP-2 rs243865 C>T and MMP-9 rs3918242 C>T gene polymorphisms were closely related to cancer susceptibility." (PMID 31192912, 2019). "Moreover, MMP9 is also associated with cancer and metastasis by regulating apoptosis and the allocation of VEGF75." (PMID 30796272, 2019). "Elevated expression of MMP-9 has been linked to shortened survival in several types of cancers." (PMID 33817161, 2019). "One of the major similarities between mf- and cancer cell line- exposed monocytes is the significant upregulation in the mRNA levels of IL-1β (associated with inflammation or M1 phenotype), MMP9 (associated with angiogenesis), and TGM2 (associated with M2 phenotype)." (PMID 29668679, 2018). "In addition to cancers, MMP-9 is also associated with the pathologies of some other diseases, including autoimmune diseases and cardiovascular diseases, which will not be addressed in this review." (PMID 30262739, 2018). "MMP-9 expression has been associated with increased metastatic potential in many cancer types." (PMID 29682175, 2018).
cancer (continued). "The alternative activated pathway of NF-κB is induced by Casp12 might be implicated in MMP-9-mediated carcinoma cell invasion." (PMID 28380444, 2017). "In addition, the methylation analysis of MMP9 gene was performed comparing 6 normal cell lines with 7 cancer cell lines using the bioinformatic ENCODE DNA Methylation RRBS." (PMID 27115178, 2016). "Elevated expression of MMP-2 or MMP-9 is associated with human cancer invasion and metastasis." (PMID 26637807, 2016). "This family, and in particular Mmp-2 and Mmp-9, have been implicated in a variety of cancers." (PMID 26654940, 2016). "Our data in this study showed the expression of NF-κB, COX-2 and MMP-9 was suppressed upon berberine treatment, indicating that the anti-invasive effect of berberine may be associated with inflammation response of cancer cells upon treatment." (PMID 27092498, 2016). "Furthermore, the expression levels of MMP-2 (molecular weight 63 kDa) and MMP-9 (molecular weight 92 kDa), representative MMPs associated with the migration of cancer cells, were downregulated following berberine treatment." (PMID 25634589, 2015). "In addition, the MMP-9 protein has been shown to be an independent risk factor for cancer recurrence in PeCa." (PMID 25908946, 2015). "MMP-2 (gelatinase A) and MMP-9 (gelatinase B) are cancer-associated zinc-dependent endopeptidases." (PMID 25563361, 2015). "Furthermore, elevated serum and tissue levels of MMP-9 are reported to be associated with cancer invasion and metastasis." (PMID 24586907, 2014). "Furthermore elevated levels of MMP-9 in the serum and urine have also been found to be associated with metastasis and poor prognosis in a diversity of cancers." (PMID 25151367, 2014). "In contrast to these reports, transgenic α1 integrin mice exhibit increased gelatinase B/MMP-9 expression and produce high level of circulating angiostatin, which reduces primary and metastatic growth of orthotopic cancers, in association with reduced angiogenesis." (PMID 24473089, 2014). "Overexpression of MMP-9 has been found to associate with the invasion and metastasis of cancer." (PMID 24476461, 2014). "Osteopontin and MMP9 are implicated in angiogenesis and cancer progression." (PMID 24216994, 2013). "TIMP-1 is a potent biological inhibitor of MMPs including MMP-9 (gelatinase B), a metalloproteinase that has been implicated as a potential therapeutic target in a wide variety of inflammatory and vascular diseases and in cancer." (PMID 23185522, 2012). "Associations between intensity of MMP-9 expression and cancer over different renal tissues." (PMID 23110201, 2012). "Our results suggests that CypA is positively regulated by gankyrin, and CypA-MMP3/MMP9 may underlie the role of gankyrin in cancer metastasis." (PMID 22913272, 2012). "Among these MMPs, MMP-2 and MMP-9 are directly linked with angiogenesis and degradation of the basement membrane collagen, and their expression and activity are correlated with metastatic abilities and prognosis of cancer." (PMID 23006512, 2012). "Hence, the T allele of the −1562 polymorphism of MMP9 gene is related to a higher transcriptional activity of the gene and in cardiovascular illness and cancer to higher MMP-levels in biological fluids and tissues." (PMID 20037727, 2009). "MMP-2 and MMP-9 are proteinases implicated in cancer progression." (PMID 18506186, 2008). "Likewise, high level of COX-2 predicted high MMP-9 level in carcinoma cells (OR 2.7, 95% CI 1.0–7.3), but laminin-5 γ2-chain staining within carcinoma cells was inversely associated with MMP-9 expression (OR 0.22, 95% CI 0.08–0.61)." (PMID 18253113, 2008). "Thus, MMP-9 is considered as an oncogenic driver that affects the advancement of various carcinomas and is also a potential diagnostic or prognostic biomarker in several types of cancers." (PMID 40034591, 2025).